RIPK3 (receptor interacting serine/threonine kinase 3)
Diseases named in the same sentence as RIPK3 in open-access papers (continued):
Sharing a sentence is not in itself a finding about the gene and the disease.
infection (continued). "The mRNA levels of JEV decreased significantly in RIPK3-RNAi-neuro2a cells compared to vehicle neuro2a cells at different times of infection, which was consistent with the JEV-E protein levels." (PMID 32265853, 2020). "At 36 h post infection, the expression of RIPK3 underwent consistent decreased in response to necrostatin-1 treatment (P < 0.05)." (PMID 32117097, 2020). "Here, we re-evaluated the importance of RIPK3 for macrophage death during noninvasive S. Typhimurium infection and the consequence for infection outcome." (PMID 33024046, 2020). "In the present study, we showed that RIPK1 and RIPK3 were upregulated in lung tissues of severe patients dying from human infection with H7N9 virus." (PMID 31080811, 2019). "It is thus unclear why Ripk3−/− mice had a mild and transient impairment in Mtb control at 4 weeks post-infection." (PMID 29892302, 2018). "To address this, we infected BMDMs derived from wild-type (WT) and Ripk3−/− mice with an mCherry-expressing Mtb strain and analyzed mCherry fluorescence in BMDMs by flow cytometry 4 h after infection." (PMID 29892302, 2018). "During natural infection, the RHIM-dependent association of ZBP1 and RIPK3 is blocked by MCMV M45, thereby avoiding premature cell death and supporting the production of progeny virus in support of dissemination and pathogenesis." (PMID 30050136, 2018). "Immunostaining and confocal imaging of RIPK1 and RIPK3 in sort-purified HSPCs revealed distinct IFNαR-dependent changes during IOE infection." (PMID 30080899, 2018). "The authors described a 0.5 log decrease in bacterial numbers in the lungs of Ripk3−/− mice 4 weeks post-infection, in a high-dose intravenous challenge model." (PMID 29892302, 2018). "To address this question, we set out to determine the effect of pandemic Cal/09 infection on RIPK3-induced cell death in DC." (PMID 29203926, 2017). "Of the genes whose transcription is downregulated following PR8-ΔNS1 infection, 28 were dependent on RIPK3, including four on its kinase activity." (PMID 27391363, 2016). "Only ~5% of the IAV-induced transcriptome was affected to any significant extent by the loss of RIPK3, and none of the affected genes were obligate RIPK3 targets (i.e., completely dependent on RIPK3 for change in their expression levels upon infection)." (PMID 27391363, 2016). "Based on our observations that maximal differences between Ripk3-/-Casp8-/- and B6 or Ripk3-/- BMDMs occurred at 6 hours post-infection, we performed RNA-seq analysis on these three genotypes of macrophages 6 hours after LPS stimulation." (PMID 27737018, 2016). "Infection with RNA viruses triggers the formation of a RIPK1/RIPK3 complex, and inhibition of RIPK1 kinase function blocked viral-induced activation of the inflammasome." (PMID 26297639, 2015). "Importantly, SARS-CoV-2 infected R3-/- vs. WT comparisons revealed distinct signatures compared to SARS-CoV-2 infected C8/R3-/- vs. infected WT comparisons, indicating that caspase-8 exerts effects independently of RIPK3 during infection." (PMID 41233351, 2025). "Although the calculated fold changes for RIPK1 and RIPK3 phosphorylation were rather low and subject to high inter-experimental variation over the time course of infection, trends point toward an increased expression and phosphorylation of MLKL in rVSV-infected A549 and H1437 cells 16–24 hpi." (PMID 40896365, 2025). "The results showed that caspase-3 was processed into its active form immediately after infection, and phosphorylation of RIPK3 and MLKL could be detected during the early infection." (PMID 40607949, 2025). "However, both wild-type C. rodentium and ΔespL infection triggered comparable amounts of cell death in RIPK3-expressing CMT-93 cells and this death was insensitive to GSK’872 treatment." (PMID 40128366, 2025). "Therefore, the detection of apoptosis in C8/Ripk3-/- mice suggests activation of the intrinsic apoptotic pathway during infection with SARS-CoV-2." (PMID 41233351, 2025).
infection (continued). "The R1 (ICP6) encoded by herpes simplex virus (HSV)-1 and HSV-2 blocks necroptosis in human cells and naturally prevents virus-induced necroptosis triggered very early after infection of human cells by preventing ZBP1 recruitment of RIPK3 using a mechanism very much like MCMV M45." (PMID 39772130, 2024). "Similarly, R1-ICR-3 also reduced RIPK3 recruitment by endogenous ZBP1 triggered by HSV-1(ICP6mut) infection in HS68 cells." (PMID 39345610, 2024). "In addition, in a recent study showing that the RIPK3 scaffold plays a regulatory role in lung inflammation during P. aeruginosa infection, blocking the RHIM domain in RIPK3 with M45 reduced the inflammatory response to infection in vitro." (PMID 38933265, 2024). "Such mice developed BM failure upon infection or low dose polyI:C/LPS injections due to the hypersensitivity of Casp8−/− HSPCs to infection or inflammation-induced necroptosis which can be prevented by Ripk3 deletion." (PMID 38637559, 2024). "Differently from Ripk3, Mlkl mRNA is usually increased during inflammation, especially as a consequence of interferon type I and II signalling (mostly occurring during pathogen infection." (PMID 36175538, 2023). "Notably, an IFN-inducible protein, OASL1, was detected from the RIPK3 complex following MCMV-M45mutRHIM infection." (PMID 36604592, 2023). "However, in the late persistent stage at 100 days post-infection Ripk3−/− mice exhibited enhanced viral clearance kinetics across multiple organs in contrast to poor viral control in WT and Mlkl−/− infected mice." (PMID 36792599, 2023). "However, we identified that RIPK3 promotes immune dysfunction and prevents control of infection at later stages of chronic LCMV disease." (PMID 36792599, 2023). "Loss of RIPK3 or ZBP1 or the combined loss of either with a non-cleavable Caspase-8 would drive unsustainable IAV replication leading to lethal infection, compromising host viral defense and as a consequence of apoptosis and necroptosis inhibition." (PMID 36175538, 2023). "We attempted to identify a potential mechanism underlying the differential clearance kinetic in RIPK3-deficient animals, and performed unbiased RNAseq analysis of FACS-sorted virus-specific CD8+ T cells from WT and Ripk3−/− mice at 14-days post-infection with LCMV docile." (PMID 36792599, 2023). "The loss of RIPK3 or MLKL had no impact on the expansion or attrition of LCMV specific T cells as evidenced by comparable kinetics in virus-specific CD8+ T cells that recognize GP33 and NP396 across both RIPK3 and MLKL-deficient mice compared to WT mice at 8- and 35-days post infection." (PMID 36792599, 2023). "RIPK3 was shown to be essential for cytokine and chemokine initiated immune control of infection." (PMID 36792599, 2023). "This illustrates the dynamic nature of inflammatory responses during C. rodentium infection, as additional IL-22 analyses in Casp8–/–Ripk3–/– mice at 7 dpi revealed that these mice produced less IL-22 than their Casp8+/-Ripk3–/– littermates at this stage of the infection." (PMID 37080966, 2023). "At the same late time of 24 h post-infection, the Ripk3−/− BMDMs showed almost WT levels of activation of many PANoptosis molecules, consistent with the cell death phenotype we observed; however, Ripk3−/− BMDMs continued to show significantly reduced CASP1 and GSDMD activation at the 24 h timepoint." (PMID 38005819, 2023). "Necroptosis is a form of modulated necrosis that is stimulated downstream of TNFR1; relies on the activity of RIPK1 and RIPK3; is mediated by the mixed-lineage pseudokinase MLKL; and may be caused by mechanical damage, inflammation, or infection." (PMID 36632211, 2023). "In addition, a higher proportion of Ripk3-/- mice exhibited clinical signs of neurologic disease, including paresis or full hindlimb paralysis, by 14 days post infection (dpi), and this difference persisted to at least 21 dpi." (PMID 38011306, 2023).
infection (continued). "Infection of LLC-PK cells with PSaV Cowden strain showed that the interaction of phosphorylated RIPK1 (pRIPK1) with RIPK3 (pRIPK3), mixed lineage kinase domain-like protein (pMLKL) increased in a time-dependent manner, indicating induction of PSaV-induced RIPK1-dependent necroptosis." (PMID 36735696, 2023). "Finally, we assessed how inadequate intestinal C. rodentium clearance in Casp8–/–Ripk3–/– mice impacted on its systemic presence by quantifying splenic pathogen loads at distinct stages of the infection." (PMID 37080966, 2023). "In addition, there was an association between elevated circulating RIPK3 and CRP, which are indicators of inflammation and infection." (PMID 37640752, 2023). "Moreover, RIPK3 in the serum positively correlated with circulating infection and inflammatory indicators (PCT and CRP)." (PMID 37475188, 2023). "However, longer term inhibition of RIPK3/MLKL (72h post-infection) has previously been shown to extend cell viability by inhibiting necroptosis, coinciding with increased control of M. tb growth." (PMID 37000865, 2023). "By contrast, the absence of obvious leukocytic abnormalities in the RIPK3-deficient patient is consistent with the absence of serious infections other than HSE in this patient until the age of 24 years." (PMID 37083451, 2023). "Indeed, C. rodentium infection of Casp8–/–Ripk3–/–Casp1–/– mice recapitulated the infection-induced lethality of Casp8–/–Ripk3–/–Casp1/11–/– mice, while both Casp8–/–Ripk3–/–Casp11–/– and Casp8–/–Ripk3–/–Gsdmd–/– mice survived the infection." (PMID 37080966, 2023). "Since infection with hr-HPV also leads to downregulation of RIPK3 expression through a yet unknown mechanism, necroptosis is also blocked." (PMID 37197430, 2023). "In contrast, over the course of infection with Francisella tularensis, RIPK3 deficiency did not impact the magnitude of the expansion nor contraction of MAIT cell pools." (PMID 36774342, 2023). "HSV1 infection could stimulate RIPK3 within one or more neural cell types at time of direct cell infection." (PMID 36121858, 2022). "Infection with an engineered MCMV variant with a mutational disruption of the viral M45 RHIM domain core tetrad led to ZBP1- and RIPK3-dependent but RIPK1-independent necroptosis, which emphasizes the enormous contribution of this protein to immune evasion and latent infection." (PMID 36040212, 2022). "Likewise following IAV infection of Ripk3−/− mice, active vaccination and infection resulted in decreased presence of CD8+ T-cells in the lung." (PMID 35351865, 2022). "Moreover, NIBV significantly upregulates RIPK3 protein levels and RIPK3-mediated necroptosis following infection with NIBV occurring in the kidney." (PMID 36016369, 2022). "Similarly, co-deletion of ASC or caspase-8/RIPK3 with caspase-1/-11 phenocopies NLRC4 deletion during challenge with flagellin or infection with Legionella." (PMID 35563804, 2022). "This is most probably due to slower recovery of the RIPK3-deficient mice and not due to enhanced morbidity during the first 9–10 days of infection." (PMID 33976111, 2021). "This was consistent with the observation that the combined loss of caspase-8 and RIPK3 did not impair bacterial control in vivo until at least 3 weeks post-infection." (PMID 32735843, 2020). "Direct MLKL activation may also avoid the potential accumulation of RIPK3-driven oxidative stress upon stimulation of the necrosome as has been reported following TNFα/Smac mimetic treatment, pathogen infection or necrosome formation." (PMID 32826875, 2020). "Interestingly, at day 7 post-infection (time of resolution), the spleen size was augmented in all RIPK3–/–, Casp-1/11–/–, and Casp-1/11–/–/RIPK3–/– DKO mice in comparison to WT." (PMID 32328060, 2020). "However, in primary human monocytes and macrophages, there was also a contribution of RIPK3-mediated necroptosis 24 h post infection." (PMID 32385301, 2020).
infection (continued). "In the early phase of infection, RIPK3–/– mice showed more aggressive onset of JE than WT mice." (PMID 32265853, 2020). "RIPK3-induced necroptosis has been suggested as a means by which S. Typhimurium evades immune responses during systemic infection and thus exacerbates infection." (PMID 33024046, 2020). "Indeed, infection with the vaccinia virus (VV), a poxvirus strain, sensitizes the cells to TNF- induced necroptosis, while the RIPK1 or RIPK3 deficient cells are resistant to the TNF-induced necroptosis." (PMID 31509938, 2019). "However, the protein level of RIPK1 was decreased upon infection while the amount of RIPK3 protein was increase at 3hpi and decreased at 12hpi when compared with mock-infected cells." (PMID 31165725, 2019). "We next sought to characterize whether a ZBP1/RIPK3 necrosome-like complex was formed during infection." (PMID 30050136, 2018). "The secretion of certain pro-inflammatory cytokines including IL-1β by macrophages and dendritic cells can be induced by RIPK3 under certain conditions, with Ripk3 deletion attenuating inflammasome activation and IL-1β processing following LPS stimulation or infection with certain RNA viruses." (PMID 29892302, 2018). "We thus examined whether there were any differences in immunological responses to Mtb infection in Ripk3−/− versus WT mice at 4 weeks post-infection." (PMID 29892302, 2018). "Caspase 8 enzymatic activity negatively regulates necroptosis via RIPK1 and RIPK3 instability, and we found that type I IFNs limited caspase expression during infection, providing a potential mechanism whereby IFNα/β facilitate pathologic RIPK1-RIPK3 interaction and downstream RIPK3 activation." (PMID 30080899, 2018). "Alternatively, the role of RIPK3 may be more prevalent in tissues that re-model frequently or tissues that must function as a barrier for infection." (PMID 28151480, 2017). "Thus, O. tsutsugamushi reduces RIPK3 levels during infection." (PMID 40430799, 2025). "To understand if necroptosis plays role in acute LCMV infection and disease, we infected WT, RIPK3-deficient (Ripk3−/−) or MLKL-deficient (Mlkl−/−) mice with a low dose LCMV Armstrong, an acute variant of the virus, and analyzed the immune response at day 8 post infection." (PMID 36792599, 2023). "Moreover, despite higher absolute numbers of MAIT cells in Ripk3−/− mice than WT mice following infection of mice with F. tularensis, our fold change analysis suggested that the relative expansion and contraction of MAIT cells is unperturbed in the absence of RIPK3." (PMID 36774342, 2023). "Casp1/11/8–/–Ripk3–/– mice, however, should lack the cell death pathways initiated by NLRC4 (via Caspase-1 or Caspase-8), Caspase-11, and TNFα, and our results above suggest that these mice might be highly susceptible to infection." (PMID 36645406, 2023). "Interestingly, RIPK3-deficient cells behaved like TNF-KO cells: upon MVA-infection, RIPK3-deficiency conferred no protection." (PMID 34711816, 2021). "Because B. thailandensisvgrG5ΔCTD was not efficiently cleared from Casp8/Ripk3/Casp1/11−/− BMDMs, we hypothesized that Casp8/Ripk3/Casp1/11−/− mice may be more susceptible to infection than WT mice." (PMID 34154417, 2021). "However, we considered the possibility that macrophage responses in the context of Ripk3 deletion may differ in the presence of other immune cells and cytokines that are involved in infection in vivo." (PMID 29892302, 2018). "Thus, we examined whether targeting RIPK3 signaling in vivo promoted the clearance of Mtb by using Ripk3−/− mice and a physiologically relevant aerosol model of infection." (PMID 29892302, 2018). "However, equal proportions of WT and RIPK3 HSCs were observed after infection, demonstrating intrinsic RIPK3 kinase activity does not mediate HSC loss." (PMID 30080899, 2018).
infection (continued). "We observed that caspase-8 was inhibited throughout the infection, and the necroptosis pathway was also suppressed due to the inhibition of phosphorylation and activation of RIPK1, RIPK3, and MLKL, mediated by the TNFα and NF-κB signaling pathways." (PMID 40607949, 2025). "This places both RIPK3 and RIPK1, critical regulators of necroptosis, at the center of determining cell fate during pathogen infection." (PMID 40434815, 2025). "To further determine the necrotic nature of a fusogenic and non-fusogenic OV-mediated death, we analyzed the expression and phosphorylation of the necroptosis mediators, RIPK1, RIPK3, and MLKL, over the time course of infection by western blot analysis." (PMID 40896365, 2025). "During infection, ZBP1 responds to IAV and forms the ZBP1-RIPK3 complex, which then facilitates recruitment of RIPK1 and further forms ZBP1-PANoptosomes with ZBP1/RIPK3/RIPK1/FADD/CASP8 as the main components." (PMID 40568592, 2025). "GFP-tagged GSDMD was expressed in RIPK3 expressing HeLa (HeLa-RIPK3) cells, in which we previously reported that co-treatment of TNF and TAK1 inhibitor mimics pathogen infection and induces mitochondrial ROS." (PMID 40533460, 2025). "First, parasite replication was measured in naïve WT, RIPK3−/−, and MLKL−/− BMDM following infection with mCherry Type II T. gondii (ME49) tachyzoites." (PMID 41055414, 2025). "RIPK1 degradation with R1-ICR-3 treatment prevented RIPK3, especially activated RIPK3 (pRIPK3), from binding to ZBP1 during HSV-1(ICP6mut) infections." (PMID 39345610, 2024). "As anticipated, the interaction between RIPK3 and ZBP1 was stronger following ΔVP22 or ΔVP22 (51–246 aa) infections than following infection with viruses with intact VP22 1–50 aa domain." (PMID 39475237, 2024). "Z-DNA binding protein 1 (ZBP1) is another innate immune sensor that recognizes Z-RNA generated during IAV-infection leading to RHIM-mediated recruitment and activation of receptor interacting kinase 3 (RIPK3) followed by apoptosis and necroptosis." (PMID 38778049, 2024). "Accordingly, infection or cellular stressors can lead to cell death by the combinatory crosstalk of pyroptotic, apoptotic, and necroptotic molecules (like ZBP1, RIPK1, RIPK3, CASP1, CASP8, and NLRP3, MLKL, and GSMDs) to effectively control pathogenic invasion." (PMID 38590437, 2024). "PPV infection induced a significant increase in p-RIPK3 and p-MLKL 24 h post-infection when apoptosis was inhibited; however, the expression and cleavage of Caspase-8 was not changed." (PMID 39614405, 2024). "Following the infection of cells by bacteria or viruses, ZBP1 recognizes heterologous nucleic acids, activates RIPK3, and forms a ZBP1-RIPK3 complex." (PMID 39614405, 2024). "Activation markers of ZBP1-mediated necroptosis, including RIPK3 phosphorylation (pRIPK3) and MLKL phosphorylation (pMLKL), were attenuated in R1-ICR-3-treated HT29-hZBP1 cells during HSV-1(ICP6mut) infection." (PMID 39345610, 2024). "Subsequently, the phosphorylated RIPK1, RIPK3, and MLKL promoted the ROS accumulation of mitochondria and Ca2+ influx in RAW264.7 cells, further exacerbating cell necrosis and persistent infection." (PMID 37175724, 2023). "Consistent with our cell death data, we found that the activation of these PANoptosis molecules was completely abrogated at 12 h post-infection in IAV-infected Zbp1−/− BMDMs, and we observed a similar phenotype in Ripk3−/−Casp8−/− BMDMs." (PMID 38005819, 2023). "We probed cell lysates for phosphorylated RIPK1, RIPK3 and MLKL by Western blot over a time course from 15–90 min post-infection." (PMID 37000865, 2023). "During infection VV induces TNF production, driving RIPK3 activation and consequent MLKL induced necroptosis." (PMID 36175538, 2023). "Infection of TNF-primed Ripk3-/-Casp8DA BMDMs resulted in substantial increase in cell death, as measured by PI uptake, relative to unprimed Ripk3-/-Casp8DA BMDMs." (PMID 37279255, 2023).